MUC1 (mucin 1, cell surface associated)
Diseases named in the same sentence as MUC1 in open-access papers (continued):
Sharing a sentence is not in itself a finding about the gene and the disease.
tumor (continued). "The cellular expression of MUC1 SP domain on MUC1 positive tumor cell-lines and primary naïve cells." (PMID 24416403, 2014). "ELISA measurements show that although the amplitude of the response varies, presence of MUC1-specific IgG antibodies can be detected in serum of tumor bearing mice and the levels are significantly higher in mice with ovarian and oviduct tumors." (PMID 25078979, 2014). "Anti-MUC1 SP antibodies specifically bind MUC1-expressing tumor cells in an unmanipulated, heterogeneous cell population, with minimal nonspecific binding to naïve BM cells." (PMID 24416403, 2014). "Payne and co-workers synthesized tumor vaccines containing per-glycosylated MUC1 glycopeptide and lipopeptide of Pam3CS with an efficient condensation reaction, and they demonstrated that different glycosylations affected the immune response." (PMID 26344745, 2014). "MUC1 regulates multiple pro-tumor activities including proliferation, epithelial to mesenchymal transition, and inhibition of apoptosis in tumor cells." (PMID 24605110, 2014). "Tumors showed increased expression of MUC1 glycoprotein and triggered de novo antibodies in tumor bearing hosts, mimicking the immunobiology seen in patients." (PMID 25078979, 2014). "MUC1 activity is also known to contribute to Ttzm resistance, and a high circulating level of galectin-3 in patient serum is related to tumor progression." (PMID 25499743, 2014). "MUC1 blocks degradation and nuclear accumulation of β-catenin, a protein with multiple regulatory functions that thus is influential in tumor development, and MUC1 regulates gene transcription by forming a complex with nuclear factor κB." (PMID 25499743, 2014). "The neoplasm metastasis associated genes KRT20, tumor protein D52 (TPD52), MUC1, and KIT are upregulated in the poor prognosis tumors while homeobox B1 (HOXB1) is downregulated." (PMID 24634783, 2014). "The expression of MUC1 appeared at the plasma membrane and in the cytoplasm of the majority of tumor cell types." (PMID 24911657, 2014). "An analogous study in the orthotopic Panc02/MUC1+ tumor model gave similar results (2-way ANOVA, P < 0.001)." (PMID 24681847, 2014). "MUC1 is overexpressed and aberrantly glycosylated in most cancers, and elevation of the MUC1 level plays an important role in tumor invasion and metastasis." (PMID 24722639, 2014). "It is most probable that a combination of more than one of the proposed mechanisms leads to the strong yet specific, membranal MUC1 SP presence detected via staining intensity of tumor cell lines and patient-derived PC with the R23IgG antibodies." (PMID 24416403, 2014). "A conditionally replicating adenovirus (CRAd) in which the E1a gene is driven by the tumor-specific promoter Mucin 1 (MUC-1) has also been generated." (PMID 24884806, 2014). "Although MUC1 staining seems to be related to a better differentiation state of the tumor cells since it can be considered as a differentiation marker, most of the reports suggested an association of MUC1 expression with a worse prognosis." (PMID 24810688, 2014). "MDSCs were isolated from the BM of B16 MUC1 and B16 Neo-tumor-bearing mice and compared to MDSCs isolated from KCM and KCKO-tumor-bearing mice." (PMID 24605110, 2014). "The findings strongly suggest a role for MUC1 in tumor induced immune suppression; possibly via the generation of suppressive MDSCs." (PMID 24605110, 2014). "Exposing LNCaP cells to enzalutamide significantly enhanced their sensitivity to MUC1-specific CTL-mediated lysis relative to tumor cells exposed to vehicle (P < 0.01)." (PMID 25344864, 2014). "They found that “dual-targeted” T cells kill Her2 + tumor cells efficiently and proliferate in a manner that requires the co-expression of MUC1 and Her2 by tumor cells in vitro." (PMID 25241075, 2014).
tumor (continued). "Alternatively, this phenomenon can be linked to inability of the SPase to cleave all the translated MUC1 molecules which are overproduced in the transformed tumor cell." (PMID 24416403, 2014). "Among various family members, MUC1 and MUC4 are implicated in tumor growth, intracellular and extracellular signaling, tumor–stromal interactions, metastasis, and resistance to chemotherapeutic agents and in immunity." (PMID 24671186, 2014). "MUC-1 is expressed in normal tissue and upregulated on several tumors, where it can exert immunosuppressive effects and attain tumor growth." (PMID 24834066, 2014). "It was also reported that abnormal E-cadherin expression in tumor cells was correlated to MUC1 expression, which was observed in the cases of poor prognosis or advanced stage." (PMID 24810688, 2014). "MUC1-CT acts as a co-transcription factor to activate genes involved in tumor progression and metastasis." (PMID 24504508, 2014). "The mean percentage positivity for biomarkers in tumour vs. normal tissue was as follows: for KOC 74% vs. 0.4%; for S100P 75% vs. 0.3%; for mesothelin 75% vs. 4%; and for MUC1 75% vs. 18% (p < 0.0001 for all tumour vs. normal comparisons)." (PMID 25071419, 2014). "Second, significantly higher numbers of monocytic MDSCs and lower numbers of granulocytic MDSCs was detected in B16 MUC1 versus B16 Neo-tumor-bearing mice." (PMID 24605110, 2014). "MUC1 expression is related to a poor prognosis of various human neoplasms and plays an important role in tumor invasion and metastasis, but in our cases MUC1 expression was only related to positive lymphatic invasion." (PMID 25551773, 2014). "The fluorenscence microscopic results demonstrated that tumor cells stained with FITC-conjugated Muc1 appearedgreen fluorenscent and DCs stained with PE-conjugated CD11c were red fluorenscent." (PMID 25036145, 2014). "Having shown that MUC1 expression was associated with an increase of cell viability, migration, invasion, apoptosis resistance and tumor growth, we studied the impact of MUC1 overexpression on the major intracellular signaling pathways by Western blot." (PMID 24504508, 2014). "In these studies, injections of MUC1 cDNA vaccine to tumor-bearing mice were able to induce tumor regressions." (PMID 23509794, 2013). "The combination of an anti-MUC1 mAb with β-glucans significantly increased 20% the rate of RMA-S-MUC1 tumor regression in C57BL/6 mice." (PMID 23739801, 2013). "These clones were able to recognize MUC1+ HLA-A*0201+ tumor cell lines from different types of cancer: breast, pancreatic, and renal." (PMID 23509794, 2013). "Overall, we show that microRNAs regulated by MUC1 have the potential to influence proliferation, invasion, metastasis, tumor metabolism, and drug resistance." (PMID 24143167, 2013). "Another strategy which has been developed to improve MUC1 cDNA vaccination consists of combining the vaccine with a tumor-cell-death inducer, such as a cDNA interfering with the expression of ANT2, a protein implicated in carcinogenesis." (PMID 23509794, 2013). "FBXW7 is a known tumor suppressor but the presence of MUC1 in UPD region is surprising as it is a well-known oncogene." (PMID 24204606, 2013). "We show that DC/tumor activated with combined TLR2 and TLR4 are most effective inducer of MUC1-specific CTL activation compared with solitary TLR2- or TLR4-activated DC/tumor on a per fusion cell basis." (PMID 23555011, 2013). "PankoMab (Glycotope, Germany) is a murine anti-human MUC-1 antibody that binds to a carbohydrate-induced conformational tumor epitope of MUC-1, greatly increasing its tumor specificity." (PMID 23509731, 2013). "We studied the polarization of cytokine response in MUC1.Tg mice at different phases of tumor development." (PMID 23496860, 2013). "Since then, different teams have used these TG mice to study tolerance against MUC1 and how to induce in vivo an MUC1 tumor-specific T-cell response." (PMID 23509794, 2013).
tumor (continued). "A number of tumor-associated or epithelial-specific genes are used in the detection of CTCs of different types of cancer, including CK, Her2, CEA, MUC1, EpCAM, EGFR, hTERT, survivin, c-met, FN1 and several other mRNA markers." (PMID 23599802, 2013). "With the goal of studying the immunogenicity of MUC1 in vivo and of developing MUC1-based cancer immunotherapy, human MUC1 transgenic mouse (TG mice) tumor models were set up by the group of Papadimitriou." (PMID 23509794, 2013). "Firstly, we describe the differences between MUC1 expression in healthy cells and tumor cells which renders MUC1 more immunogenic when it is expressed by tumor cells." (PMID 23509794, 2013). "MUC1 has been proposed to be a key modulator of several signaling pathways in epithelial cancers that affect tumor cell invasion, proliferation and survival." (PMID 24072600, 2013). "MUC1 glycoprotein is often found overexpressed and hypoglycosylated in tumor cells from numerous cancer types." (PMID 23509794, 2013). "In another study, Wright and colleague showed that tumor burden influences the quality of adoptively transferred MUC1 specific CTL." (PMID 23509794, 2013). "It has subsequently been shown that the glycosylation structures of MUC1 expressed by normal breast cells and tumor cells are different." (PMID 23509794, 2013). "Normally, MUC-1 expressed on tumors is immunogenic owing to overexpression and tumor-restricted hypoglycosylation." (PMID 23509731, 2013). "Together, these findings suggest that augmentation of CTL activity specific for MUC1 and restricted by HLA-A2 is generated by fusions of ethanol-treated tumor cells and TLRs-DCs in vitro." (PMID 23717436, 2013). "In a murine model, the use of MUC1-specific 90Yttrium-labelled moAb PAM4 in combination with gemcitabine as a radiosensitiser increased inhibition of tumor growth and prolonged animal survival." (PMID 23509731, 2013). "Immunohistochemical analysis of tumor xengrafts further confirmed that NANOG overexpression enhanced tumor development and increased expressions of cancer stemness protein-SOX2 and MUC1 in tumor xengrafts." (PMID 23662114, 2013). "To examine the HLA-A2 restrictive MUC1-specific CTLs induction by DC/tumor, we used the MUC1 and HLA-A2 positive tumor cell line, PANC-1 cells." (PMID 23555011, 2013). "The aim of this study was to compare the expression of MUC1, E-cadherin and β-catenin in multicentric/multifocal tumors with their expression in unifocal tumors of identical tumor size according to TNM staging in order to detect potential differences." (PMID 23890049, 2013). "This study was designed to assess the role of multiple immune-suppressive cytokines including TGF-β1 derived from tumor cells, which were used for FC preparations on the induction of MUC1-specific CTLs restricted by HLA-A2." (PMID 23717436, 2013). "Using MUC1 DNA complexed to oxidized or reduced mannan was more immunogenic (T-cell responses, IFN-gamma secretion, low dose administration, and tumor protection) compared to MUC1 DNA alone." (PMID 24228179, 2013). "Since NANOG knockdown suppressed mammosphere formation and reduced levels of SOX2 and MUC1 in tumor xengrafts, we next tried to determine if propagation of CD24−/lowCD44+ breast CSC subpopulation in MCF-7 cells is also regulated by NANOG." (PMID 23662114, 2013). "The Muc1 gene is one of the markers included in a commercial test (AdnaTest BreastCancer®) which combines immunomagnetic tumor cell selection targeting EpCAM and MUC1 followed by multiplex RT-qPCR for the transcripts EpCAM, MUC1 and HER2." (PMID 24058517, 2013). "MUC1 is naturally expressed, and tolerogenic responses can occur in patients leading to tumor escape against the immune system." (PMID 23509794, 2013). "In our study, HIF1A, similarly to NOTCH1, correlated with most of the other tumor markers but less with MUC1 or NKX2-1 as markers of lung physiology." (PMID 23028920, 2012).
tumor (continued). "This resulted in tumor-to-normal ratios of 4.8 ± 0.56, 2.3 ± 0.27, 1.2 ± 0.095, 4.6 ± 0.62, and 2.4 ± 0.88 for CD44v6, MUC1, Mammaglobin, CAXII, and TfR, respectively." (PMID 22695343, 2012). "Future studies need to investigate other existing antibodies in regard to their specificity and sensitivity of detecting MUC1 epitopes and should focus on differences regarding each tumour type." (PMID 23241107, 2012). "We further show that the inhibitor peptide of MUC1 (GO-201) inhibits the activity of MUC1-c and results in reduced cell proliferation and viability of tumor cells both in vivo and in vitro." (PMID 22912777, 2012). "It should be noted that MUC1 expression loses apical plasma membrane polarity in tumor cells and instead shows a broad cytoplasmic/membrane expression pattern." (PMID 22905162, 2012). "In contrast, very few CD8+ T cells targeting the glycopeptide epitopes of extracellular tumor antigens (e.g. mucin 1 (MUC1)) have been described." (PMID 23189185, 2012). "MUC1 is overexpressed and aberrantly glycosylated in human neoplasms, particularly adenocarcinomas of the pancreas and breast, and its expression correlates with metastasis." (PMID 22586492, 2012). "By repeated NCL couplings of mucin tandem repeats, MUC2 and MUC1 tandem repeat polypeptides have been prepared, and such polypeptides are useful for the development of anti-tumor vaccines." (PMID 23015828, 2012). "We believe that the present report is the first to show that peripheral tolerance in MUC1.Tg mice supports the tumor growth in vivo." (PMID 23028615, 2012). "Further characterisation of MUC1 expression on stem/progenitor cells will be instrumental for the future application of MUC1-based tumour vaccines." (PMID 23285151, 2012). "We found 46% ER/PR-positive tumours, overexpression of EGFR (15%), α-IGF1R (25%), p110α (19%), pAkt (28%), pBad (22%), pmTOR (23%), pMAPK (24%), MUC1 (80%), PTEN loss (20%), and PTEN promoter hypermethylation (20%)." (PMID 22454081, 2012). "MUC1 protein is an attractive target for tumor-specific drug delivery owning to its overexpression in most adenocarcinomas." (PMID 22384115, 2012). "Recent studies have demonstrated that the MUC1 cytoplasmic domain plays an important role in tumor cell invasion and anchorage-independent growth." (PMID 22586492, 2012). "Treg/Teff ratios at the tumor site in MUC1.Tg mice were significantly greater than those in B6 mice 10 days after injection of tumor cells." (PMID 23028615, 2012). "Here, we showed for the first time, that MUC1-specific peripheral tolerance operates in MUC1.Tg mice and supports the tumor growth in vivo." (PMID 23028615, 2012). "It has been suggested that the hypo-glycosylated state of MUC1 in tumour cells contributes to the increased immunogenicity through damasking antigenic sites on the protein." (PMID 23166757, 2012). "To assess such possibility, we analyzed the type of T cells infiltrating in tumor tissues in MUC1.Tg mice." (PMID 23028615, 2012). "In these trials, there is a clear concern not only over targeting the MUC1 tumor antigens, but also over boosting either innate and/or adaptive immune responses." (PMID 24970145, 2012). "One strategy to achieve tumor specificity is the use of tumor- or tissue-specific promoters, such as MUC1, PSA, or PS2, to drive adenoviral genes that are essential for replication." (PMID 22640485, 2012). "Each tumour cell line used in this study showed cytoplasmic expression of MUC1, and the positivity was mainly observed in a granular pattern." (PMID 22726603, 2012). "Including TfR, Mammaglobin, and MUC1 to the panel of highly tumor-specific markers GLUT1, MET, EGFR, IGF1-R, CAIX, and HER2 increased the detection rate from 45.5% to 49.8% (TfR), 56.4% (Mammaglobin), and 98.1% (MUC1), respectively." (PMID 22695343, 2012). "The present study reveals that MUC1-specific peripheral tolerance, which supports the growth of tumor cells expressing MUC1, plays an important role in MUC1.Tg mice." (PMID 23028615, 2012).
tumor (continued). "Strong pMAPK expression in 24% (22/93) of the tumours predominated in those of low grade (P=0.029); MUC1 was overexpressed in 80% of the analysed tumours (77/96) but without significant association with clinicopathological features." (PMID 22454081, 2012). "The intrinsic qualitative and quantitative differences of MUC1 in tumour and non-tumour cells, together with its inherent immunogenicity, makes it particularly suitable for its development as a cancer vaccine." (PMID 23166757, 2012). "Apt-Dox was found capable of carrying doxorubicin into MUC1-positive tumor cells, while significantly reducing the drug intake by MUC1-negative cells." (PMID 22384115, 2012). "The results were comparable with conventional immunohistochemistry resulting in tumor-to-normal ratios of 3.93 ± 0.14, 2.74 ± 0.46, 1.54 ± 0.11, and 1.66 ± 0.066 for CD44v6, MUC1, Mammaglobin, and CAXII, respectively." (PMID 22695343, 2012). "Although we used sequential sections from one paraffin embedded tumor tissue obtained from each patient for MUC1 and cMet staining, we cannot conclude that over-expression of MUC1 and c-Met occurs in the same cells in HCC tissues." (PMID 22962849, 2012). "This test is based on the detection of three tumor-associated transcripts (GA733-2, MUC-1, and HER2) by reverse transcription-polymerase chain reaction (RT-PCR) after immunomagnetic enrichment of tumor cells." (PMID 22894854, 2012). "Addition of less tumor-specific markers theoretically increased the detection rate to 98.1% using MUC1, but of the less tumor specific markers only CD44v6 met the desired 3-fold tumor-to-normal tissue ratio measured by image analysis." (PMID 22695343, 2012). "We found that growth of tumor cells expressing MUC1 was enhanced in MUC1.Tg mice, and the effect was likely due to the local effects of Treg cells." (PMID 23028615, 2012). "Most of the primary tumours and metastases were positive for EpCAM, MUC-1 and Her2 but in some cases, EpCAM and especially MUC-1 expression disappeared." (PMID 22591372, 2012). "Cell invasion by MUC1-expressing tumour cells can be suppressed by over-expression of the micro RNA, miR-145, which directly interacts with MUC1 mRNA in the 3′ UTR region." (PMID 23166757, 2012). "To investigate the role of GalNAc glycosylation in vivo for this MUC1 model tumor antigen, we immunized Balb/c mice and HLA-A2 transgenic mice with degMUC1 with and without GalNAc glycosylation." (PMID 23189185, 2012). "Tolerance to MUC1, suppression of MUC1-specific T cells, and promotion of tumor growth were observed when MUC1.Tg mice were used as recipients." (PMID 23028615, 2012). "The inhibition of MUC1 function by GO-201 was seen to prevent tumor growth and progression in the treatment group significantly as compared with the untreated group." (PMID 22912777, 2012). "The less tumor-specific targets MUC1 (90.7%), CD44v6 (63.8%), Mammaglobin (16.8%), TfR (14.5%), and CAXII (8.7%) were in general more frequently expressed than the tumor-specific targets." (PMID 22695343, 2012). "In order to deliver Dox to MUC1-positive tumor cells, an aptamer-doxorubicin complex (Apt-Dox) was formed by intercalating doxorubicin into the DNA structure of the MA3 aptamer." (PMID 22384115, 2012). "Both antibodies were internalised by this MUC1 tumour cell line which can explain the low efficacy observed in vitro and in vivo." (PMID 21264246, 2011). "In the 123I series, gamma camera images showed uncertain tumour retention of 123I-anti-MUC1, comparable with 123I-anti-TNP retention." (PMID 21603241, 2011). "MUC1 contributes to tumor progression of adenocarcinomas and therefore its downregulation was predicted to affect the malignant properties of cancer cells, including proliferation, apoptosis, migration, invasion and cell-cell aggregation." (PMID 22073229, 2011).